CLSPN (claspin)
Diseases named in the same sentence as CLSPN in open-access papers (continued):
Sharing a sentence is not in itself a finding about the gene and the disease.
cancer (continued). "This analysis revealed that Claspin, Timeless, and CHK1 are overexpressed in a coordinated manner in these three cancers whereas the checkpoint sensors ATR, RAD17, and RAD9 are not." (PMID 30796221, 2019). "In fact, the normal tissues displayed either no or faint claspin immunoreactivity, whereas a moderate/high positivity was observed in 16% of the CIN1, 76% of the CIN2, 87.5% of the CIN3 and 93.3% of the cancers." (PMID 22731782, 2012).
tumor (27 papers, 2014 to 2025). "Recently, CLSPN has been reported to associate with tumorigenesis, tumor metastasis and therapeutic resistance." (PMID 37268895, 2023). "We propose that where high Claspin expression is associated with poor patient survival, this reflects its role in allowing these tumours to deal with high levels of DNA replication stress." (PMID 36240068, 2022). "In addition, aged heterozygous knockout CLSPN mice were more susceptible to tumor development than CLSPN wt aged-matched littermates." (PMID 41009395, 2025). "Together, these findings indicate a mechanism by which CLSPN loss subsequent to SLF2 deficiency may explain the tumor suppressor function of SLF2, while SLF2 also acts as a regulator of several factors involved in cell cycle progression and DNA repair." (PMID 37485814, 2023). "In contrast, where low levels of Claspin are associated with poor survival this may indicate either intrinsically lower levels of genomic instability or that the tumours have engaged other pathways to deal with rapid unstable proliferation." (PMID 36240068, 2022). "Therefore, the consequences of variations in Claspin expression may be more complex than currently described and depend on the other mutational events of the tumor." (PMID 41009395, 2025). "Generally, it was observed that several pathways involved in tumor resistance to either chemo- or radiation therapy involved downstream stabilization and sustained expression of Claspin." (PMID 41009395, 2025). "In sum, Claspin inactivation seems to facilitate malignant transformation, a feature consistent with a role for Claspin as a tumor suppressor." (PMID 41009395, 2025). "Over-expression of Claspin provides tumor cells with high levels of survival signals mediated by the Akt pathway." (PMID 41009395, 2025). "Claspin inactivation seems to be an essential event in oncogenesis, a feature compatible with a role as a tumor suppressor." (PMID 41009395, 2025). "This indicates the potential utility of this antibody in future veterinary research to test the effects of inhibiting Claspin, or to detect the protein expression level in different tumor samples." (PMID 37655260, 2023). "Considering the tumor‐relevant molecular mechanism downstream of SLF2 loss, we identified loss of CLSPN." (PMID 37485814, 2023). "Subsequently, we combined TCGA and GTEx datasets to further validate the CLSPN expression differences in multiple normal tissues and tumor tissues (P < 0.05)." (PMID 37268895, 2023). "The immunohistochemistry result of subcutaneous tumor indicated that knockdown CLSPN significantly down regulated CCNA2, CCNB1, CDK1, CDK2 and Ki67 expression." (PMID 37268895, 2023). "The GEO (Gene Expression Omnibus) dataset further validated the influence of CLSPN on the prognosis of tumor patients in clinical cohort." (PMID 37268895, 2023). "In our study, we found for the first time that CLSPN expression had a close relationship with immune cell infiltration among multiple tumor types." (PMID 37268895, 2023). "Many studies have documented increased levels of Claspin in tumour versus normal tissue, or correlated an increase in Claspin expression with malignant progression." (PMID 36240068, 2022). "Claspin overexpression is reported to contribute to tumor proliferation in several human solid tumors such as carcinomas of the lung, ovary, uterine cervix, stomach, and kidney." (PMID 34240817, 2021). "As a checkpoint adaptor protein, Claspin directly bridges the ATR/Chk1 pathway, which is the hallmark of tumor progression." (PMID 34071237, 2021). "From the remaining differentially expressed genes, 11 belonged to the apoptosis pathway, in which E2F1 and CLSPN were deregulated in 14 and 12 tumour types, respectively." (PMID 28387377, 2017). "Taken together, our findings demonstrated a novel function of HERC2/USP20 in coordinating CHK1 activation by modulating CLASPIN stability, which ultimately promotes genome stability and suppresses tumor growth." (PMID 25326330, 2014).
tumor (continued). "Since then, many data have been produced supporting our thesis that have brought about the discussion of whether Claspin acts as an oncogene or a tumor suppressor." (PMID 41009395, 2025). "Claspin may similarly be a tumor suppressor that can act as an oncogene in specific contexts or due to specific mutations." (PMID 41009395, 2025). "All these studies support a role for Claspin as a tumor suppressor." (PMID 41009395, 2025). "In these tumors, Claspin stabilization may promote tumor cell survival through activation of Chk1-mediated G2 checkpoint responses and cell cycle arrest." (PMID 41009395, 2025). "It has also been shown that USP20 depletion was associated with increased chromosomal aberrations, malignant transformation, and tumor growth, and that the malignant phenotype could be significantly suppressed by ectopic expression of Claspin." (PMID 41009395, 2025). "It has been argued that, as tumor cells are usually under RS due to oncogene activation, the higher levels of Claspin observed in higher-grade lesions could simply reflect their higher proliferative rates as described for Ki-67." (PMID 41009395, 2025). "As tumors become out of control and their stemness features increase (e.g., undifferentiation, and high proliferation and replication rates), Claspin expression increases, which suggests that tumor cells exploit the physiological role of Claspin in response to RS and in the FPC." (PMID 41009395, 2025). "It is possible, however, that Claspin has a role in the initial stages of cell dedifferentiation, as the silencing of Claspin in early oncogenesis may compromise transmission of the histone code to daughter tumor cells, a process crucial for epigenetic memory." (PMID 41009395, 2025). "Thus, in some instances, it would be beneficial for the tumor to exploit Claspin’s functions in checkpoint activation and RS response, namely to increase survival and evade cell death (bottom)." (PMID 41009395, 2025). "In addition, Claspin silencing will prevent checkpoint activation and fork stabilization in tumor cells." (PMID 41009395, 2025). "The correlation of Claspin expression with clinical parameters at that moment fails to fully explain Claspin’s role in the tumor pathophysiology and does not prove a causative role for Claspin in the clinical parameters studied." (PMID 41009395, 2025). "The inactivation of Claspin in early oncogenesis may therefore allow for dedifferentiation of tumor cells and contribute to their acquisition of stem cell features." (PMID 41009395, 2025). "Together, these data suggest that Claspin inactivation is an important event in carcinogenesis, and that Claspin may act as a tumor suppressor." (PMID 41009395, 2025). "CLSPN was significantly upregulated in tumor tissues when compared with normal tissues." (PMID 37268895, 2023). "We analyzed various tumor samples to explore the genetic alteration status of CLSPN." (PMID 37268895, 2023). "To investigate whether CLSPN expression could predict tumor progression, we selected five typical MMR genes, and evaluated their association with CLSPN." (PMID 37268895, 2023). "Knockdown CLSPN significantly reduced the tumor growth rate in A549 and PC9 cells." (PMID 37268895, 2023). "Furthermore, the CLSPN expression in diverse tumor cell lines was demonstrated with significant differences based on CCLE datasets (Kruskal–Wallis test: P = 2.6e − 24)." (PMID 37268895, 2023). "Of further interest, we found a KEOPS complex member (gm6890), implicated in homologous double-strand break repair and telomere maintenance, to be strongly upregulated during tumor formation, as well as the checkpoint adaptor Claspin (CLSPN) and three chromosome 17q loci CBX2, GJC1 and LIMD2." (PMID 34638267, 2021). "CLSPN is an oncogenic gene that contributes to tumor proliferation in several human solid tumors." (PMID 34240817, 2021).
tumor (continued). "Also, in parallel with its role in checkpoint signaling, Claspin positively regulates DNA replication—overexpression of Claspin can enhance both tumor and normal cell proliferation." (PMID 29415985, 2018). "In addition, Claspin seems to play a role in the tumors’ response to chemo- and radiation therapy, acting as a pivot onto which different pathways converge to promote resistance of tumor cells to therapy." (PMID 41009395, 2025). "However, it is worth noting that the increase in Claspin expression observed in tumor samples was significantly greater than that of Ki-67, suggesting that other underlying causes may explain the increased Claspin levels." (PMID 41009395, 2025). "Therefore, Claspin may constitute an additional link between HR-HPV infection and malignant transformation, suggesting a role for Claspin in carcinogenesis as a tumor suppressor." (PMID 41009395, 2025). "Currently, whether CLSPN could influence tumor immune microenvironment remained unknown." (PMID 37268895, 2023). "Importantly, we demonstrate a tumour suppressor role for Claspin." (PMID 36240068, 2022). "In addition, CENPL, ESCO2, and CLSPN also serve important roles in tumor progression." (PMID 34556022, 2021). "Indeed, Claspin expression may vary in different phases of tumor development." (PMID 41009395, 2025). "The mRNA expression levels of STMN1, CLSPN, MDK, RNFT2, PRR11, and RNF157 were significantly increased in HCC tumor tissue; on the contrary, GHR was significantly decreased compared with normal tissues." (PMID 37542549, 2023). "It was also found that CLSPN activates the AKT signaling pathway and is co-expressed with several known tumor-related genes, such as programmed death ligand-1." (PMID 34093635, 2021). "This question becomes more relevant since a recent study showed that CLASPIN, the human homologue of Mrc1, is stabilised by the deubiquitinating enzyme USP20 during checkpoint activation and that USP20 suppresses xenograft tumor growth." (PMID 26201080, 2015). "It is also generally believed that tumor cells may adapt to oncogene-induced RS by modulating the intensity of the ATR–Claspin–Chk1 response, as ATR and Chk1 haploinsufficiencies enhance oncogene-induced tumor development." (PMID 41009395, 2025). "In addition, RT-qPCR and immunohistochemical staining also showed that celastrol administration downregulated Claspin, Bcl-2, METTL3, and YTHDF3 in the xenograft tumor tissues." (PMID 38110764, 2023). "Nevertheless, Claspin stabilization and Chk1 activation after GSK3-β inhibition might contribute to promoting survival, and thereby counteracting tumour removal." (PMID 31362447, 2019). "Importantly, we also found that in low-grade NSCLC, increased expression of Claspin, Timeless, and CHK1 (but not ATR, RAD9, and RAD17), correlates with the aggressiveness of the tumor." (PMID 30796221, 2019).
infection (6 papers, 2012 to 2025). The state of being infected such as from the introduction of a foreign agent such as serum, vaccine, antigenic substance or organism. "HPV-induced malignant transformation seems to require E7-mediated Claspin degradation, which compromises host cell checkpoint activation, thereby facilitating infection." (PMID 41009395, 2025). "Using Claspin f/- cells that we previously established, Claspin can be knocked out by infection of Ad-Cre viruses." (PMID 36671510, 2023). "Chk1 phosphorylation, induced by various stresses, was reduced in Claspin knockout conditions (after Ad-Cre infection;)." (PMID 36671510, 2023). "At 2 days after infection, non-coding Claspin siRNA or control siRNA was introduced into the cells for two days, and then the cells were treated with 2 mM HU for 1 hr or non-treated before harvest." (PMID 31889509, 2019). "Upon Ad-Cre infection, endogenous Claspin was knocked out, and growth and DNA replication were examined." (PMID 27401717, 2016). "In general, Claspin degradation appears to be a key event in most oncovirus-mediated infections that alleviates the host cell ATR–Chk1 checkpoint pathway, allowing the escape of infected cells from surveillance mechanisms and their entry into mitosis despite the presence of DNA damage." (PMID 41009395, 2025). "Since we had observed that AdΔ19K-infection of gemcitabine-treated cells decreased pChk1 levels, increased the mitotic index and reduced drug-induced Claspin accumulation, we asked whether virus promoted Claspin degradation." (PMID 26872382, 2016). "Early in infection and lymphomagenesis, STAT3 is activated, promoting activation of caspase-7, Claspin degradation, and the consequent suppression of Chk1 phosphorylation and checkpoint activation." (PMID 41009395, 2025). "Remarkably, AdΔ19K- but not Ad5-infection of gemcitabine-treated cells significantly decreased Claspin mRNA levels to almost basal after 48h." (PMID 26872382, 2016).
CLSPN also shares sentences with these, for which no sentence is quoted: anaplastic thyroid cancer (1 paper); Bladder Cancer (1); bladder urothelial carcinoma (1); Bloom syndrome (1); brain tumors (1); breast invasive carcinoma (1); breast tumors (1); cervical intraepithelial neoplasia (1); clear renal cell carcinoma (1); colorectal carcinoma (1); endometrial carcinoma (1); Eμ (1); Kidney Chromophobe (1); mesothelioma (1); myelodysplastic syndrome (1); neuroblastoma (1); non-alcoholic fatty liver disease (1); pancreatic adenocarcinoma (1); skin cutaneous melanoma (1); squamous intraepithelial lesions (1); stomach cancer (1); uveal melanoma (1).